IGF1 (insulin like growth factor 1)
Diseases named in the same sentence as IGF1 in open-access papers (continued):
Sharing a sentence is not in itself a finding about the gene and the disease.
post-traumatic stress disorder (2 papers, 2023 to 2025). An anxiety disorder precipitated by an experience of intense fear or horror while exposed to a traumatic (especially life-threatening) event. "In a male rat model of post-traumatic stress disorder (PTSD), moderate exercise was shown to increase the expression of insulin-like growth factor-1 (IGF-1) and activate the BDNF/TrkB axis, which in turn stimulates the PI3K/Akt pathway." (PMID 41169370, 2025).
postpartum depression (2 papers, 2022 to 2025). A type of clinical depression that occurs after childbirth. "Conversely, a study made in Japan involving 8042 women, found that pregnant women who had higher IGF-1 peripheral levels during the first trimester were less propense to develop postpartum depression during the first month after birth." (PMID 40141202, 2025). "An observational cohort study involving 8,791 Japanese pregnant women found that women with high serum IGF-1 levels in early pregnancy were less likely to develop postpartum depression than women with low serum IGF-1 levels." (PMID 36279393, 2022). "In this sense, higher IGF-1 levels during specific periods of pregnancy could protect against developing postpartum depression." (PMID 40141202, 2025).
pregnancy hypertension (2 papers, 2020 to 2022). "Another previous study reports that newborns who are born to mothers with pregnancy hypertension had lower cord blood IGF-1 levels compared with those born to mothers without pregnancy hypertension, and the SGA newborns showed low cord blood IGF-1 levels." (PMID 35407507, 2022).
puberty (2 papers, 2019 to 2024). The process of sexual maturation mediated by the neuroendocrine system in mammals. "Puberty is associated with increases in sex hormones (estrogens and androgens), as well as changing growth hormone (GH) and insulin-like growth factor-1 (IGF-1) levels; together this neuro-endocrine axis controls linear growth, accumulation of muscle mass, and bone mineralization." (PMID 30809514, 2019).
renal dysfunction (2 papers, 2012 to 2022). "In high-risk patients, CVM was related to IGF-1 levels, severe renal dysfunction and valvular etiology, whereas in young patients CMV was related to the high-risk pattern and serum IGF-1 levels." (PMID 35445917, 2022). "CVM was related to severe renal dysfunction (HR stages IV–V = 4.86), high-risk conditions (HR 2.25), serum IGF-1 (HR 0.42), and HF etiology (HR 5.85 and HR 1.63 for valvular and ischemic etiology, respectively)." (PMID 35445917, 2022). "In high-risk patients it was possible to highlight how the factors associated with higher mortality were IGF-1 values, the presence of severe renal dysfunction and the valvular etiology." (PMID 35445917, 2022).
Right ventricular hypertrophy (2 papers, 2017 to 2023). In this case the right ventricle is more muscular than normal, causing a characteristic boot-shaped (coeur-en-sabot) appearance as seen on anterior- posterior chest x-rays. "Smooth muscle cell (SMC)-specific deletion of IGF1 reduced the proliferation of PASMCs and attenuated hypoxia-induced pulmonary vascular remodeling, right ventricular hypertrophy, and right ventricular systolic pressure." (PMID 37731513, 2023).
schistosomiasis (2 papers, 2010 to 2022). An infectious disease caused by parasitic trematodes of the genus Schistosoma that colonize human blood vessels and release eggs that can cause granulomatous reactions leading to acute (swimmer's itch or acute schistosomiasis syndrome) or chronic disease. "Low levels of IGF-1 have been shown to be associated with the presence of hepatosplenic schistosomiasis, indicative of periportal fibrosis, in Brazil." (PMID 19818465, 2010).
schwannoma (2 papers, 2011 to 2025). A benign, usually encapsulated slow growing tumor composed of Schwann cells. "Although peripheral nerve sheath tumors are rarely reported in this context, the mitogenic properties of IGF-1 may contribute to schwannoma pathogenesis." (PMID 41479497, 2025). "HEI-193 schwannoma cells expressed IGF-1 levels comparable to A4573 cells." (PMID 22022506, 2011). "Elevated GH and insulin-like growth factor 1 (IGF-1) levels are known to stimulate cellular proliferation through mitogenic signaling pathways and have been implicated in increased overall tumor risk, although a direct causal link with schwannoma development has not been established." (PMID 41479497, 2025).
Sensory neuropathy (2 papers, 2019 to 2022). Peripheral neuropathy affecting the sensory nerves. "The association between IGF1 isoforms and hyperalgesia detected in this study is supported by reports that the administration of IGF1 is proven effective in alleviating sensory neuropathy." (PMID 35453627, 2022). "This is the first demonstration that sensory neuropathy affects cardiac miRNA expression network targeting IGF-1, SLC2a-12, EIF-4e, and ULK-2, which may contribute to cardiac diastolic dysfunction induced by sensory neuropathy." (PMID 30823517, 2019). "This IGF-1–miR-1 connection was confirmed by our data in sensory neuropathy." (PMID 30823517, 2019). "This is the first demonstration that sensory neuropathy induced by capsaicin desensitization affects cardiac miRNA expression network targeting IGF-1, SLC2a-12, EIF-4e, and ULK-2, which may contribute to cardiac diastolic dysfunction induced by sensory neuropathy." (PMID 30823517, 2019).
serous adenocarcinoma (2 papers, 2024). An adenocarcinoma that is characterized by the presence of papillary patterns and cellular budding. "In this study, we showed that IGF-1 is overexpressed in high-grade serous carcinoma (HGSC) cell lines, specifically OVCAR3 cells, at both mRNA and protein levels, being a good cell line model to study the IGF-1 inhibition via knockdown of this gene by siRNA or IGF-1R inhibition with linsitinib." (PMID 39596005, 2024).
Sheehan’s syndrome (2 papers, 2022 to 2025). "Future studies should include IGF-1 measurements and dynamic testing to further explore the role of GH in the neuropsychiatric manifestations of Sheehan’s syndrome." (PMID 40357200, 2025). "In Sheehan’s syndrome, characterized by GH deficiency, a significant decrease in CCT was found, which positively correlated with IGF-1 levels." (PMID 36431227, 2022).
Sinusoidal Obstruction Syndrome (2 papers, 2020 to 2021). "Although pre-transplant low IGF-1 was reported as associated with fluid retention and Sinusoidal Obstruction Syndrome (SOS), in a cohort of 330 patients it seems to be significantly associated with GVHD." (PMID 33488571, 2020). "IGF-1 levels were also investigated as possible predictors of sinusoidal obstruction syndrome (SOS) in patients treated with HSCT." (PMID 34959885, 2021).
Spinocerebellar ataxia type 3 (2 papers, 2022 to 2025). "Background and aims: The pathogenesis of Spinocerebellar ataxia type 3 (SCA3) is associated with dysregulation of the Insulin/IGF‐1 signaling (IIS) pathway." (PMID 40542581, 2025).
squamous intraepithelial lesion (2 papers, 2008 to 2014). "Another much more prospective study was one of the first to demonstrate a relationship between serum levels of IGF-1 and precancerous squamous intraepithelial lesions (SILs)." (PMID 25333772, 2014).
Stress urinary incontinence (2 papers, 2016 to 2024). Involuntary urine leakage synchronous with exertion, or actions such as sneezing, or coughing. "Recent animal study has shown that there are therapeutic effects of Insulin-like growth factors (IGF-1) on stress urinary incontinence in rats with simulated childbirth trauma." (PMID 27564291, 2016). "A study developed a bioactive injectable bulking agent that consists of Permacol, which is made of collagen, and recombinant insulin-like growth factor-1-conjugated fibrin micro-beads and injected the material into the bladder of the rabbit model of stress urinary incontinence." (PMID 39247652, 2024).
subarachnoid hemorrhage (2 papers, 2014 to 2020). A serious neurological disorder characterized by intracranial hemorrhage into the subarachnoid space. "Previously, we demonstrated that the conditioned medium from the culture of dental pulp-derived stem cells could alleviate neuroinflammation via an IGF-1-related mechanism in a rat model of subarachnoid hemorrhage." (PMID 32471263, 2020).
thoracic aortic aneurysm (2 papers, 2023). An aneurysm formed in the wall of the proximal portion of the descending aorta proceeding from the arch of the aorta. "Further, increased AngII-mediated and insulin-like growth factor 1–mediated signaling, independent of TGF-β signaling, is thought to drive a form of inherited nonsyndromic thoracic aortic aneurysms associated with missense mutations in the MYH11 gene." (PMID 36472907, 2023).
Ureteral obstruction (2 papers, 2013 to 2016). Obstruction of the flow of urine through the ureter. "Previous studies have shown that administration of insulin-like growth factor-1 (IGF-1) ameliorates the renal injury in a mouse unilateral ureteral obstruction (UUO) model, whereas the underlying mechanisms are not completely understood." (PMID 27301852, 2016).
Urethral stricture (2 papers, 2021 to 2023). Narrowing of the urethra associated with inflammation or scar tissue. "That study found that slow-release IGF-1 reduced formation of urethral strictures in rabbits." (PMID 37489431, 2023).
uterine cancer (2 papers, 2019 to 2021). Primary or metastatic malignant neoplasm involving the uterine corpus and/or the cervix.
acute GVHD (1 paper, 2022). "IGF-1 levels at 14 and 28 days after transplant were significantly higher in group A and were associated with a lower incidence of acute GVHD (aGVHD)." (PMID 36079847, 2022).
acute tonsillitis (1 paper, 2024). An acute inflammation of the tonsils caused by viruses or bacteria. "Moreover, IGF-1, HDL cholesterol, total protein and total bilirubin positively affect J03 Acute tonsillitis." (PMID 38487847, 2024).
adrenal crisis (1 paper, 2025). "At the time of IGF-1 measurement (495 ng/mL), the patient had been on stable hydrocortisone and levothyroxine replacement for over four weeks, with resolution of adrenal crisis symptoms." (PMID 40842744, 2025).
alcoholic cardiomyopathy (1 paper, 2009). A dilated cardiomyopathy which is associated with consumption of large amounts of alcohol over a period of years. "A decreased activation of cardiomyocyte IGF-1R by IGF-1 has been reported in a model of alcoholic cardiomyopathy and this was associated with an absence of protein synthesis after IGF-1 incubation." (PMID 19818143, 2009).
amblyopia (1 paper, 2012). Decreased vision that results from abnormal visual development. "We next assessed whether the potential for the reactivation of plasticity caused by IGF-1 treatment could be employed to promote the recovery of sensory functions from long-term deprivation using amblyopia as a paradigmatic model." (PMID 22720172, 2012). "Accordingly, we found that exogenous IGF-1 administration is effective in the treatment of amblyopia, a pathological condition that lacks of a suitable treatment in adulthood." (PMID 22720172, 2012).
Anal fistula (1 paper, 2025). An abnormal connection between the epithelialised surface of the anal canal and the perianal skin. "Notably, IGF‐1 has been implicated in enhancing the regenerative capacity of epithelial and connective tissues, which are key components involved in the healing of anal fistulas." (PMID 41199981, 2025). "Third, these findings open up new avenues for research into therapeutic modulation of IGF‐1 levels in patients with anal fistula." (PMID 41199981, 2025). "Our study demonstrated that preoperative serum IGF‐1 levels are a reliable predictor of wound healing outcomes following incision‐thread‐drawing surgery for anal fistula." (PMID 41199981, 2025). "This study highlights the prognostic value of preoperative serum IGF‐1 levels in patients undergoing incision‐thread‐drawing surgery for anal fistula treatment." (PMID 41199981, 2025). "Clinical studies have further indicated that elevated IGF‐1 levels correlate with improved healing outcomes in other types of surgical wounds, suggesting potential relevance for anal fistulas." (PMID 41199981, 2025). "Further research is warranted to explore therapeutic strategies that target IGF‐1 pathways, potentially offering new solutions to enhance recovery and minimize complications in anal fistula surgery." (PMID 41199981, 2025). "In conclusion, this study underscores the clinical significance of preoperative serum IGF‐1 levels as a prognostic marker for wound healing in patients undergoing incision‐thread‐drawing surgery for anal fistula." (PMID 41199981, 2025). "Given its critical functions in tissue repair, this study aims to investigate the prognostic value of preoperative serum IGF‐1 levels in patients undergoing incision‐thread‐drawing surgery for anal fistulas." (PMID 41199981, 2025). "This study investigates the prognostic value of preoperative serum insulin‐like growth factor‐1 (IGF‐1) levels in predicting wound healing after incision‐thread‐drawing surgery for anal fistula." (PMID 41199981, 2025). "While direct evidence linking IGF‐1 to anal fistula repair remains sparse, these findings highlight its promising role in addressing the challenges of tissue repair and regeneration in this context." (PMID 41199981, 2025). "First, preoperative measurement of serum IGF‐1 levels could become a standard part of the preoperative assessment for patients undergoing anal fistula surgery." (PMID 41199981, 2025). "Additionally, the serum IGF‐1 levels between 29 diabetic and 100 non‐diabetic patients among the 129 anal fistula patients were compared." (PMID 41199981, 2025). "Conversely, higher IGF‐1 levels correlate with better surgical outcomes, suggesting that IGF‐1 may serve as a valuable biomarker for predicting healing outcomes in patients with anal fistula undergoing incision‐thread‐drawing surgery." (PMID 41199981, 2025). "However, research on the specific relationship between IGF‐1 and anal fistula healing is limited." (PMID 41199981, 2025). "Additionally, IGF‐1's anti‐inflammatory properties may mitigate the chronic inflammation often observed in anal fistula cases, further supporting its therapeutic potential." (PMID 41199981, 2025). "Preoperative serum IGF‐1 levels are a valuable prognostic biomarker for predicting wound healing and postoperative recovery in patients undergoing incision‐thread‐drawing surgery for anal fistula, potentially guiding clinical decision‐making and patient management strategies." (PMID 41199981, 2025).
anal incontinence (1 paper, 2025). "The Wexner score for anal incontinence, which evaluates postoperative anal function, was significantly lower in the high IGF‐1 group than in the low IGF‐1 group at both 7 days (p < 0.001) and 14 days post‐surgery (p < 0.01)." (PMID 41199981, 2025).
ankylosis (1 paper, 2019). Fixation and immobility of a joint. "Eruption of the bioengineered teeth gradually progressed over 10 weeks after transplantation in both control and IGF1-treated groups without any pathological observations, such as ankylosis or bone defects." (PMID 30675004, 2019).
anovulation (1 paper, 2024). The absence of ovulation. "High levels of insulin lead to high levels of IGF-1 and androgens, resulting in anovulation." (PMID 38671840, 2024).
antidiuretic hormone deficiency (1 paper, 2018). "As for pituitary function, antidiuretic hormone deficiency (80%) was the most frequent endocrine symptom, followed by FSH/LH (50%), ACTH (30%), TSH (20%), and GH/IGF1 (10%) axis deficiency in sequence." (PMID 29755523, 2018).
aortic atherosclerosis (1 paper, 2023). A atherosclerosis that involves the aorta. "We reported previously that insulin-like growth factor 1 (IGF-1) reduced aortic atherosclerosis and promoted features of stable plaque in a murine model." (PMID 36602878, 2023). "This is consistent with our recent report that MF-specific IGF-1 overexpression downregulates MMP9 in peritoneal MFs and decreases aortic atherosclerosis in Apoe–/– mice." (PMID 36602878, 2023).
aortic valve disease (1 paper, 2021). "Moreover, DPP4 induced valvular calcification and promoted calcific aortic valve disease progression by inhibiting autocrine insulin-like growth factor-1 (IGF-1) signaling." (PMID 34497344, 2021).
aplastic anemia (1 paper, 2024). Anemia resulting from bone marrow failure (aplastic or hypoplastic bone marrow). "In addition, HSC ferroptosis is also implicated in other human diseases characterized by HSC loss such as Fanconi anemia and aplastic anemia, highlighting a broader therapeutic potential of IGF1 in a number of BM failure syndromes." (PMID 38802843, 2024).
Apnea (1 paper, 2020). Lack of breathing with no movement of the respiratory muscles and no exchange of air in the lungs. "Respective contribution of age, gender, BMI, and apnea severity to low IGF-1 levels in multivariate analysis (below the median)." (PMID 32655494, 2020). "Respective contribution of age, gender, waist circumference, and apnea severity to low IGF-1 levels (below the median)." (PMID 32655494, 2020).
ascending aortic aneurysm (1 paper, 2025). "In accordance, either knockdown of Tnfα or Igf1 in CX3CR1+ macrophages reduced vascular inflammation, as evidenced by the downregulation of Mcp1, Il6, and Cxcl2, and subsequently ameliorated both aortic root and ascending aortic aneurysm progression as well as related aortic wall pathologies." (PMID 39817456, 2025).
asthenozoospermia (1 paper, 2025). "MOS ameliorates gossypol-induced asthenozoospermia by remodeling the gut microbiota and activating IGF-1/PI3K/mTOR signaling, thereby improving sperm motility and reducing apoptosis." (PMID 41561043, 2025). "In this study, MOS activated the IGF-1/PI3K/mTOR axis and improved progressive motility, in line with evidence that rescuing Akt/mTOR signaling (e.g., in ornidazole-induced asthenozoospermia) improves sperm quality partly by curbing excessive autophagy." (PMID 41561043, 2025).
autoimmune neuropathies (1 paper, 2018). "In conclusion, our studies support the potential use of IGF-1 for the treatment of autoimmune neuropathies, such as CIDP." (PMID 29615658, 2018).
autonomic neuropathy (1 paper, 2015). An inherited or acquired peripheral neuropathy affecting the autonomic nervous system. "Correlation of serum average hGH and IGF-1 x ULN level of acromegalic patients with cardiovascular data and autonomic neuropathy parameters." (PMID 25915951, 2015).
autosomal dominant cerebellar ataxia (1 paper, 2014). A clinically and genetically heterogeneous group of neurodegenerative diseases characterized by a slowly progressive ataxia of gait, stance and limbs, dysarthria and/or oculomotor disorder, due to cerebellar degeneration in the absence of coexisting diseases. "The objective of this clinical open-label trial was to test the safety, tolerability and efficacy of IGF-1 therapy for autosomal dominant cerebellar ataxia (ADCA) patients." (PMID 26331037, 2014). "The primary aim of this study was to demonstrate the safety and tolerability of IGF-1 therapy for patients with autosomal dominant cerebellar ataxia (ADCA)." (PMID 26331037, 2014).
Azoospermia (1 paper, 2025). Absence of any measurable level of sperm,whereby spermatozoa cannot be observed even after centrifugation of the semen pellet. "This caused a marked improvement in the morphological and immunohistochemical pattern of the spermatogenic epithelium in cases of long-term nonobstructive azoospermia, which was attributed to an increase in VEGF-A, TGF-β, and IGF-1 factors." (PMID 40870495, 2025).